NES (nestin)
Diseases named in the same sentence as NES in open-access papers (continued):
Sharing a sentence is not in itself a finding about the gene and the disease.
brain tumors (48 papers, 2005 to 2026). "There is also an association between highly tumorigenic cell subsets in brain tumors and the expression of the markers nanog, nestin, Oct4, and Sox2." (PMID 37833934, 2023). "Mice expressing the TVA receptor under the regulation of a nestin promotor were infected with RCAS virus encoding for KrasG12D to create GBM-like brain tumors with Kras in nestin-positive cells." (PMID 35446393, 2022). "Nestin is a marker often associated with neural progenitor and glial cells, which have been shown to comprise stromal cell populations within brain tumors." (PMID 24349039, 2013). "In this GE system, the tv-a gene is stably inserted into a host and controlled by a cell type- or tissue-specific promoter such as the nestin promoter, which is activated in neural and glial progenitor cells—the cells implicated as brain tumor initiating cells (BTICs)." (PMID 28358926, 2017). "In brain tumors, nestin-positive cells are associated with a perivascular cancer stem cell niche." (PMID 17615543, 2007). "Although other studies have suggested that changes in the intermediate filament proteins in brain tumors are associated with tumor malignancy and invasiveness, the role of nestin molecules in the nucleus of tumor cells still remains unclear." (PMID 16457706, 2006). "In patients with brain tumors, nestin-expressing neural precursor cells (NEPs) increase the expression of IFN-γ and upregulate Shh ligands following radiation exposure, which aids in the regeneration of nerve cells by NEPs." (PMID 40799240, 2025). "Next, we compared protein lysates from the human frontal brain with those from different Nestin+ brain tumor samples (first diagnosis samples)." (PMID 39039193, 2024). "Expression of the embryonic stem cell markers nanog, nestin, Oct4, and Sox2 is critical for the progression of various human malignancies, including brain tumors." (PMID 37833934, 2023). "Both lines gave rise to highly invasive brain tumors as ascertained by immunohistochemical staining with an antibody specific for human nestin and had comparable rates of tumor growth." (PMID 38136258, 2023). "In vivo, GL261 cells have been shown to express different general stem cell markers such as CD133 and nestin while exhibiting infiltrative capacity of brain-tumor derived mesenchymal stem cells positive for Sox2, nestin, Sca-1, CD9, CD44 and CD166." (PMID 33374542, 2020). "Upregulated nestin expression has been detected in different brain tumors and tumors derived from CNS tissues, such as pilocytic astrocytomas, and malignant gliomas including glioblastoma multiforme." (PMID 30337660, 2018). "An immunocytochemical analysis of a representative TS sample (TS15-88) identified cells expressing markers associated with stem cells and brain tumor stem cells, including CD133 and nestin." (PMID 27708549, 2016). "Nuclear transport and presence of IF proteins has been demonstrated for tail-less cytokeratin 8, 18, and 19 in 3T3 fibroblasts, for vimentin in nasopharyngeal carcinoma lymph node metastasis, for nestin in various brain tumors, and for desmin in BHK21 cells." (PMID 26787680, 2016). "This niche was discovered when Nestin+/CD133+ cells were found along the capillaries of brain tumors." (PMID 26729169, 2015). "Neural stem cells have been shown to be embedded within a vascular microenvironment, CD133+, nestin+ tumour cells (containing the GCSCs) being located next to capillaries in brain tumours." (PMID 23998913, 2013). "These cells possessed different molecular genetics and cell biology characteristics compared with common brain tumor cells since they expressed neural stem cell markers, such as nestin, Musashi-1, Bmi-1 and CD133." (PMID 23251243, 2013).
brain tumors (continued). "For example, nestin was considered to be a specific brain tumor stem cell marker but was later found to be expressed in progenitor cells during differentiation." (PMID 23251243, 2013). "Future studies knocking out additional Myc cofactors such as TIP60, p300, and JARID factors in NSC employing the same nestin-cre are likely to shed further light on Myc function in brain development and brain tumors." (PMID 22745758, 2012). "Nestin has been detected in brain tumors such as pilocytic astrocytomas and malignant gliomas including GBM." (PMID 19108713, 2008). "These cancer stem cells derived from brain tumors formed NSCs and were positive for the neural stem cells markers Nestin and CD133." (PMID 16987412, 2006). "Nestin expression in human brain tumors has been detected by immunohistochemical techniques in a number of studies, and nestin positivity has been detected in the processes of tumor cells in tissue sections." (PMID 16457706, 2006). "We previously found that ectopic expression of ING5 increased the expression of the Oct4, Olig2 and nestin neural stem cell markers in stem-like brain tumour initiating cells (BTICS) in vitro while promoting self-renewal, preventing lineage differentiation, and increasing stem cell pools." (PMID 39787145, 2025). "Additionally, we stained for Nestin to detect the presence of stem/progenitor cells in the brain tumor tissue." (PMID 39770529, 2024). "Desmin has been detected in nuclei of BHK21 cells and nestin in nuclei of brain tumor cells." (PMID 26787680, 2016). "Interestingly, similar to some brain tumor cell lines, we detected in some SD-MSCs the presence of Nestin by nuclear staining, which suggests the possible involvement of gene expression." (PMID 24586857, 2014). "Nestin is an intermediate filament expressed by normal neural and brain tumor stem cells." (PMID 25238146, 2014). "rQNestin34.5 was initially created to target oHSV killing to nestin-positive brain tumor cells." (PMID 19156211, 2009). "In a second step we looked for the expression by SON vessels of nestin or vimentin, two intermediate filament proteins that are expressed by the endothelial cells constituting newly formed capillary vessels in the developing CNS or in brain tumors." (PMID 15790414, 2005). "In addition to the ZIKV receptors, we further characterized all cell lines for the expression of embryonic stem cell markers Nanog, Nestin, Oct4, and Sox2, as these are critical receptors for the progression of various human malignancies, including brain tumors." (PMID 38398205, 2024). "Further IHC staining of tumor for HGA markers including GFAP, Sox2, nestin, and Ki-67 confirmed the HGA status of the brain tumors." (PMID 35814428, 2022). "In particular, brain tumors have high levels of ALDH, CD133, and Nestin, with ALDH+ and CD133+ cells accounting for about 8% and 17–40%, respectively, in pediatric MB." (PMID 34731160, 2021). "BTICs with high expression of the stem cell markers, Nestin and CD133, are localized near capillaries in brain tumors, and this vascular niche is apparently critical for stem cell renewal." (PMID 30917521, 2019). "In the Nestin-Cre; PdgfraK/+; INK4A/Arf−/− cohort, mice generally succumbed to fibrosarcomas by 15 weeks, before brain tumors were detectable." (PMID 25683249, 2015). "Cocultures of the Nestin+/CD133+ cells with primary human endothelial cells were shown to maintain a greater population of self-renewing, undifferentiated brain tumor cells compared to the control group." (PMID 26729169, 2015). "In this context, nestin, BLBP and GRIA1 are potential biomarkers predicting sensitivity to this drug in brain tumor cells." (PMID 25531110, 2014).
brain tumors (continued). "It has been reported that brain tumor-derived cancer stem cells express high levels of the membrane glycoprotein CD133 and the cytoskeletal protein nestin." (PMID 23826381, 2013). "For brain tumors, this involves GFAP or Nestin driven expression of the bacteriophage protein Cre, which removes sections of DNA between E. Coli specific DNA sequences known as loxP domains." (PMID 19814820, 2009). "Similarly, in the perivascular niches in brain tumors, a cellular subpopulation of brain tumor stem–like cells (BTSCs) with NSC marker expression, including nestin and CD133, has also been identified." (PMID 35847909, 2022). "In previous studies, BTICs with high expression of the stem cell markers Nestin and CD133 were localized near capillaries in brain tumors, suggesting that the tumor microenvironment may influence BTIC function." (PMID 30917521, 2019). "Brain tumor allograft sections derived from mouse GFP+ green fluorescent NF53 brain tumor‐initiating cells showed expression of HMGA2 and stem cell marker nestin in GFP+ NF53 brain tumor cells." (PMID 28500786, 2017). "Surprisingly, a previous study using the zebrafish nestin promoter to drive conditional expression of the zebrafish version of KrasG12V did not result in brain tumors." (PMID 25644510, 2015). "More than 50% of animals in the mutant cohorts GFAP-Cre; PdgfraK/+; INK4A/Arf−/− and Nestin-Cre; PdgfraJ/+; INK4A/Arf−/− harbored highly proliferative areas in the brain, reflecting early and occasionally more advanced stages of brain tumor growth." (PMID 25683249, 2015). "Nestin and CD133 were reported in a variety of brain tumours." (PMID 23998913, 2013). "This is further supported by the diffuse staining of nestin in our specimens, as opposed to cancer stem cells, which purportedly represent only a minor-fraction of the entire brain tumor cell population." (PMID 18817556, 2008). "It has been reported that TSC expressing the markers Nestin and CD133 in a variety of brain tumors." (PMID 19108713, 2008). "While Type 1 PCs (Nestin-/NG2+) do not have infiltrative or angiogenic activity, Type 2 PCs (Nestin+/NG2+) infiltrate and participate in brain tumor neovascularization." (PMID 38791110, 2024).
breast carcinoma (38 papers, 2010 to 2026). "Several studies also assessed the potential diagnostic and prognostic value of co-expression of nestin and some other biomarkers in breast cancer." (PMID 32467665, 2020). "Previous studies investigated the potential prognostic and clinicopathological association of nestin expression with breast cancer patients." (PMID 32467665, 2020). "While FOXA1 and GATA3 are significant predictors of favorable outcome in breast carcinoma (longer disease-free interval and overall survival), Nestin expression is associated with a more unfavorable prognosis." (PMID 30819139, 2019). "In the present study, FOXA1 and Nestin expression in breast cancer metastases was associated with specific breast cancer subtypes (luminal phenotype versus triple-negative breast cancer metastases)." (PMID 30819139, 2019). "When stratifying for TNP status, Nestin was significantly associated with reduced breast cancer specific survival in univariate survival analysis in the TNP absent group (log-rank test, p = 0.003), but not in the TNP present group." (PMID 28439082, 2017). "Nestin protein expression was associated with reduced breast cancer specific survival (p = 0.002, Series I)." (PMID 28439082, 2017). "In summary, Nestin was strongly associated with germline BRCA1 related breast cancer, a basal-like phenotype, reduced survival, and stemness characteristics." (PMID 28439082, 2017). "In conclusion, Nestin was associated with germline BRCA1 related breast cancer, a basal-like phenotype, as well as high-grade tumour features and reduced survival by multivariate analysis." (PMID 28439082, 2017). "Our findings, on protein and mRNA levels, strongly indicate that Nestin is associated with BRCA1 related breast cancer, the basal-like phenotype, high-grade tumour features and reduced survival with independent significance." (PMID 28439082, 2017). "Among non-basal cases, defined by absence of the ER− HER2− CK5+ profile or ER− HER2− P-cadherin + profile, Nestin was significantly associated with poorer breast cancer specific survival (log-rank test, p = 0.003 and p = 0.004, respectively)." (PMID 28439082, 2017). "Our data indicated that Nestin expression in breast cancer tissues was associated with poor survival of Chinese patients with triple-negative breast cancer." (PMID 25056574, 2014). "Previous studies have shown that Nestin expression is associated with the disease progression and poor prognosis in breast cancers, particularly for those with advanced lymph node metastasis." (PMID 25056574, 2014). "Our previous study showed that Nestin is expressed in human breast cancer tissue, and that its expression was associated with lymph node metastasis in a cohort of breast cancer patients." (PMID 25056574, 2014). "Our previous study shows that Nestin and other stemness factors are expressed in breast cancer tissues, and that their expression is associated with poor survival of patients with breast cancer." (PMID 25056574, 2014). "In breast cancer, nestin expression is associated with shorter survival and is an independent prognostic factor." (PMID 22580387, 2012). "NES (Nestin), a cytoskeleton-associated class VI IF protein, is a neuronal stem/progenitor cell marker expressed in progenitor cells of various tissues, including central nervous system tumors, lung cancer, and breast cancer." (PMID 33718128, 2021). "We suggest that the reported cut-off value of serum Nestin and the presence of C/T polymorphism can be used to assess the risk of females for developing breast cancer and might be of potential benefit in screening the disease." (PMID 33584136, 2021). "Future work will concentrate on reproducing the reported results in a bigger cohort of the breast cancer group to investigate serum Nestin and HOTAIR gene polymorphism in different subgroups of breast cancer patients according to their histopathological and molecular subtype." (PMID 33584136, 2021).
breast carcinoma (continued). "Therefore, we performed this meta-analysis to elucidate the prognostic and clinicopathological association of nestin expression with breast cancer." (PMID 32467665, 2020). "As for the underlying basis of nestin on tumor growth, Wnt signaling seems to be required, as depleting nestin via siRNA transfection downregulated activation of Wnt/β-catenin, which is critical for the proliferation of human breast cancer stem cells." (PMID 31126068, 2019). "Nestin, a cytoskeleton‐associated class VI IF protein, is a neuronal stem/progenitor cell marker that is expressed in progenitor cells of various tissues, including central nervous tumors 30, lung cancer, 31 and breast cancer." (PMID 27891816, 2017). "Nestin overexpression has been reported in metastatic breast cancers, (especially in triple-negative breast cancers), and has been associated with poor prognosis in a Caucasian breast cancer cohort." (PMID 25056574, 2014). "Thus, in addition to being a marker of basal-like features, Nestin might have predictive value in testing breast cancer patients for BRCA1 germline mutations, although details concerning analytical and clinical validity should be further studied." (PMID 28439082, 2017). "The transcriptional activation of nestin can lead to the self-protection of breast cancer cells to drugs, resulting in drug resistance." (PMID 40799240, 2025). "Immunofluorescence assays identify CD105+Vimentin+ MSCs in lung metastases of a mouse melanoma model and Nestin+ MSCs in metastatic lung tissues of MMTV-PyMT transgenic mouse mammary tumors." (PMID 40676710, 2025). "A specific subset of NG2+/Nestin+ BM-MSCs, known to promote hematopoietic stem cell quiescence, was discovered to induce dormancy in breast cancer cells by the release off TGFβ2 and BMP7." (PMID 40676710, 2025). "Our study demonstrated that the induction of LncRNA ENST869 induced the death of breast cancer cells by regulating Nestin expression that was activated by Chidamide treatment." (PMID 35444938, 2022). "There is clear evidence showing that the expression of Nestin is increased in a variety of tumor tissues including breast cancer, and is closely related to tumor malignancy." (PMID 35444938, 2022). "During this process, Nestin is involved in the pharmacological action of Chidamide against breast cancer cells." (PMID 35444938, 2022). "After studying nestin-positive microvascular density in breast cancer patients, Nowak and her colleagues concluded that a high level of nestin expression is characteristic of newly formed tumor vessels." (PMID 35453578, 2022). "Nestin is a key player in influencing the pharmacological activity of Chidamide and an essential factor in drug resistance of breast cancer cells." (PMID 35444938, 2022). "Patients with breast cancer had a median (Min-Max) of serum Nestin 31.3 (6.7-167.3 pg/mL), while control subjects had a median (Min-Max) of serum Nestin 42.3 (25.7-315.95) pg/mL." (PMID 33584136, 2021). "Using the Youden index, the best cutoff value for serum Nestin to differentiate normal subjects and patients with breast cancer was 39.9 pg/mL." (PMID 33584136, 2021). "The study also aimed at evaluating the possibility of using Nestin and HOTAIR gene rs12826786 polymorphism as possible screening tools to identify patients with breast cancer." (PMID 33584136, 2021). "A recent study based on Western patients has shown that Nestin is preferentially expressed in basallike breast carcinomas, predominantly expressed in triple-negative breast cancers, and suggested the use of Nestin as a marker for triple-negative breast cancer." (PMID 33584136, 2021). "So far, Nestin has been evaluated in breast cancer patients only on a tissue level using an immunohistochemistry technique for diagnostic and prognostication purposes." (PMID 33584136, 2021). "The study also specified a cut-off value of 39.9 pg/mL serum Nestin to discriminate patients affected with breast cancer from normal subjects." (PMID 33584136, 2021).